ZEB2 (zinc finger E-box binding homeobox 2)
Diseases named in the same sentence as ZEB2 in open-access papers (continued):
Sharing a sentence is not in itself a finding about the gene and the disease.
tumor (continued). "Moreover, LPE18:1 also increased the invasive ability of tumor cells, although it did not alter the expression of EMT-related markers such as N-cadherin, E-cadherin, or ZEB2." (PMID 41354870, 2025). "However, simultaneous deletion of both murine Zeb2 and Zeb1 in murine MLL-AF9 AML settings was found to significantly increase the overall survival of mice transplanted with MLL-AF9 secondary tumor cells compared with nontreated vehicle-treated controls." (PMID 39200378, 2024). "Of note, neither in tumour samples nor in the cell lines could we detect a correlation between S100 proteins and the other EMT-TFs, ZEB2, TWIST1 or SNAIL2." (PMID 31123345, 2019). "Notably, other important EMT-related markers such as SNAI1, SNAI2, ZEB1, ZEB2 and TWIST1 at the invasive tumor front were not thoroughly examined in these reported studies." (PMID 26214683, 2015). "As (a) adjuvant chemotherapy is intended to kill cancer cells at secondary sites and (b) ZEB2 protein expression in secondary CRC has never been studied, we analysed 30 paired samples from patients who underwent surgical resection of primary CRC tumours and synchronous/metachronous liver metastases." (PMID 33931939, 2021). "Moreover, ZEB2 binds to the miR-200 promoter to inhibit its transcription, resulting in the formation of a negative feedback loop, which further stimulates the EMT of tumor cells." (PMID 25846512, 2015).
cancer (412 papers, 2009 to 2026). A tumor composed of atypical neoplastic, often pleomorphic cells that invade other tissues. "The zinc-finger E-box binding proteins 1 and 2 (ZEB1 and ZEB2) have been associated with malignancy in several types of cancer." (PMID 38473317, 2024). "It has been demonstrated that the high level of the ZEB2 mRNA is associated with poor patient prognosis and increased cancer stem cell-like properties." (PMID 38751602, 2024). "Among them, previous studies demonstrated that ZEB2 exerts considerable influences on cancer cells, cancer stem cells, and nervous system development, which is a risk factor for vascular diseases such as AS." (PMID 37001814, 2023). "Many forms of cancer, including breast, lung, ovarian, colorectal, gastric, and pancreatic cancers, have been linked to an upregulation of ZEB2." (PMID 37927751, 2023). "The upregulated EMT-inducers—Zeb2, Foxc2 and Inhba—have also been implicated in promoting cancer stem-cell and metastatic properties." (PMID 32581213, 2020). "Expression of EMT transcription factors (e.g., TWIST, SNAIL, SLAG, ZEB1, and ZEB2), which favor migration, invasion, and metastasis, causes cancer cells to switch from an epithelial to a mesenchymal phenotype." (PMID 33371469, 2020). "This study suggests that invasion is linked to cancer cell survival and angiogenesis by ZEB2 during cancer progression, and increases our understanding of the pathways via which EMT-inducing transcription factors regulate the complex process of metastasis." (PMID 29416649, 2018). "ZEB2 expression is also reported to be associated with poor prognosis of several types of cancer, although less frequently than ZEB1." (PMID 28618162, 2017). "In terms of mechanism, miR-338-3p directly targeted zinc finger E-box-binding protein 2 (ZEB2) and metastasis-associated in colon cancer-1 (MACC1)." (PMID 25945841, 2015). "We demonstrated here the impact of ZEB2 on migration and anchorage-independent cell growth in Hey cancer cells, and we esteblished the functional association between HuR and ZEB2." (PMID 26136338, 2015). "Our results reveal that the ZEB2 locus, implicated in multiple diseases including cancer, is a far more complex region than is currently understood." (PMID 25798919, 2015). "Binding of ZEB1 and ZEB2 to the E-cadherin E-boxes has been implicated in the regulation of E-cadherin expression in multiple human cancers." (PMID 25197668, 2014). "Binding of ZEB1 and ZEB2 to the spaced E-cadherin E-boxes has been implicated in the regulation of E-cadherin expression in multiple human cancers." (PMID 25197668, 2014). "Previous reports also demonstrated increased levels of ZEB2 transcripts in association with invasion and metastasis in advanced stage cancers." (PMID 23658743, 2013). "Previous studies also showed increased levels of ZEB2 transcripts in association with invasion and metastasis in cancers with advanced stages." (PMID 22393452, 2012). "Notably, ELF3 loss in bile ducts, commonly observed in cancers, leads to ZEB2 and EMT-related protein upregulation, reducing cell-cell junction proteins and increasing cell motility." (PMID 40204777, 2025). "The ZEB2 gene has been linked to the promotion of cancer stem cell qualities, chemoresistance, and immune evasion in several forms of cancer in addition to its role in promoting invasion and metastasis of cancer cells." (PMID 37927751, 2023). "Upregulated Zeb2 has an association with the progression of cancer." (PMID 35057823, 2022). "Future studies to further elucidate the exact mechanism underlying the ZEB2-related histone modification process may be helpful to develop novel cancer therapies." (PMID 35606881, 2022). "Taken together, ZEB2 expression was associated with poorer prognosis in OV and other cancers." (PMID 35723302, 2022). "Previous studies suggest that ZEB2 is associated with a bad prognosis in numerous kinds of cancer." (PMID 35723302, 2022).
cancer (continued). "High levels of ZEB2 are associated with metastasis of various cancers, including CRC." (PMID 33863999, 2021). "Clinical data showed that ZEB2 expression was positively associated with Sp1 expression, and that the expression of both of these factors had prognostic significance for predicting survival in cancer patients." (PMID 29416649, 2018). "The association between ZEB2 and Sp1 could also be targeted to develop novel therapies against cancer." (PMID 29416649, 2018). "Other cancer-associated genes in Cluster B include ZEB2, NOTCH1, and FAT1." (PMID 26939613, 2016). "ZEB1 and ZEB2, has been demonstrated implicated in many cancers as EMT Key factors." (PMID 27861158, 2016). "The mechanism underlying high protein stability of Zeb2 in cancer cells, however, is still unclear." (PMID 25460509, 2015). "Furthermore, the overexpression of FOXM1 leads to the acquisition of an EMT phenotype by activating the mesenchymal cell markers ZEB1, ZEB2, Snail2, E-cadherin, and vimentin, which are associated with increased spheroid-forming capacity and cancer stem cell surface markers (CD44 and EpCAM)." (PMID 36613925, 2022). "Notably, ZEB1 and ZEB2 are implicated in chemoresistance in a variety cancer types." (PMID 29849953, 2018). "ZEB2 mRNA expression was 1.7-fold lower in cancer tissue as compared to normal pancreatic tissue, but higher protein amounts were determined in Western blot analysis." (PMID 41481650, 2026). "Zeb2 is substantially associated with the progression, malignancy, and prognosis of gastrointestinal malignancies, and Zeb2 can affect the EMT process of cancers through the Wnt/β-Catenin pathway." (PMID 40109856, 2025). "For example, members of the miR‐200 family such as miR‐200a, miR‐200b, miR‐200c, miR‐141, and miR‐429, can suppress EMT in multiple cancers by targeting the 3′‐UTR of ZEB2." (PMID 41117067, 2025). "In vitro, ex vivo, and in animal models of metastasis, the FBXW7-Zinc-finger E-box-binding homeobox-2 (ZEB2) axis affects critical characteristics of cancer cells, including stemness/dedifferentiation, chemoresistance, and cell migration." (PMID 41373479, 2025). "It has been reported that miRNA-200c closely interacts with the ZEB1 and ZEB2 proteins and prevents invasion in cancer cells through this complex." (PMID 40728965, 2025). "The ZEB2 protein also regulates the epithelial–mesenchymal transition, a process essential for growth and development, wound healing and cancer metastasis." (PMID 39941075, 2025). "Recent studies have highlighted the close association of ZEB2 with EMT, indicating that ZEB2 plays a pivotal role in cancer development and progression." (PMID 40689207, 2025). "Several studies have identified ZEB2 as the critical EMT transcription factor whose expression is elevated in a variety of cancers, including NSCLC." (PMID 41002380, 2025). "Evaluating proteins involved in epithelial-mesenchymal transition(EMT) and cancer stem cell properties, we observed a significant decreasein ZEB2 with miR-205 overexpression (NOK-SK2 pcDNA/miR-205) comparedto the control (NOK-SK2 pcDNA)." (PMID 41476518, 2025). "ZEB2, a 2-handed zinc finger/homeodomain protein, has indispensable functions during early fetal development and cancer progression." (PMID 40510028, 2025). "Another aspect of research concerning ZEB2’s role in cancer was its function in resistance development." (PMID 40510028, 2025). "According to these studies, circRNAs regulate ZEB1 and ZEB2, and more research is needed to understand ZEB2 regulation by circRNAs in cancers." (PMID 38733529, 2024). "Expression profiling of EMT regulators showed gradual over-expressions of ZEB1 (8, 20, and 42 folds) and ZEB2 (4, 10, and 18 folds) in respective histological cancer grades." (PMID 38751602, 2024). "MiR-200 family miRNAs repress the expression of ZEB1 and ZEB2, thereby preserving the epithelial phenotype of cancer cells." (PMID 37460540, 2023).
cancer (continued). "In recent years, various studies have analyzed the impact of the zinc finger E-box-binding homeobox 1 (ZEB1) and zinc finger E-box-binding homeobox 2 (ZEB2) homologous transcription factors on carcinogenesis and cancer progression." (PMID 37174083, 2023). "This interaction blocks the splicing of a large intron located in the 5'UTR of ZEB2 which contains an internal ribosome entry site (IRES) critical for Zeb2 expression, thus promoting EMT of cancer cells through upregulating Zeb2 protein levels." (PMID 37215575, 2023). "When Zeb2 and Twist1 were both inhibited, the metastasis was markedly suppressed in a mouse CRC model, suggesting that Zeb2 and Twist1 contribute to cancer cell migration." (PMID 36768876, 2023). "In the process of EMT transformation, up-regulated expression of transcription factors, such as Snail1, Twist1, Zeb1, and Zeb2, can increase the migration and invasion of cancer cells." (PMID 37115802, 2023). "According to reports, miR-200s can affect ZEB1 and/or ZEB2 expression in many types of cancer, such as gastric cancer, non-small lung cancer and oral squamous cell carcinoma." (PMID 37239035, 2023). "ZEB1 and ZEB2 are highly expressed in several cancers, including BC, pancreatic cancer, HCC, and lung cancer." (PMID 37444447, 2023). "The role of ZEB2 in cancer appears to be complex and multifaceted overall, and it probably varies based on the particular cancer type and environment." (PMID 37927751, 2023). "Mechanically, we showed that BATF2 inhibits programmed death-ligand 1 expression in cancer cells by inhibiting the PI3K–AKT pathway where ZEB2 plays an important role in this process." (PMID 37777155, 2023). "The evidence that ERK1/2 activate EMT core transcription factors like SNAIL, SLUG, TWIST, ZEB1, and ZEB2 is mainly obtained from cancer cell studies." (PMID 37009481, 2023). "miR-205 also regulates EMT by targeting ZEB1 and ZEB2 and inhibits cancer cell migration and invasion in PCa." (PMID 35454801, 2022). "We investigated the correlation of ZEB2 with prognosis and infiltrating immune cells in various types of cancer, including OV." (PMID 35723302, 2022). "To identify the correlation between ZEB1 and ZEB2 expression, we analyzed this correlation in 32 cancer types using the TIMER database." (PMID 35723302, 2022). "In the present study, we investigated ZEB2 in various types of cancer, based on The Cancer Genome Atlas (TCGA) data from public databases." (PMID 35723302, 2022). "In bladder cancer, CAF-derived TGF-β1 induces the expression of EMT-specific markers, such as ZEB2 proteins, in cancer cells and increases cancer invasiveness through ZEB2NAT transcript." (PMID 35488263, 2022). "ZEB2 regulates gene expression by interacting with specific activators or repressors in various cancers." (PMID 35723302, 2022). "ZEB-2 is a promotor of cancer progression and EMT and then combined treatment managed to modulate the effect of CDDP on the mesenchymal transcription factor ZEB-2." (PMID 36500446, 2022). "We have also examined the levels of the EMT-TFs such as TWIST1, SNAIL, SLUG, ZEB1, and ZEB2 because targeting these factors has been suggested as potential cancer therapeutics." (PMID 35774120, 2022). "Recent studies have shown that ZEB2 promotes peritoneal metastasis, through the process of regulating invasive cells and tumorigenesis of cancer cells in high-grade serous ovarian cancers (HGSOCs)." (PMID 35723302, 2022). "Conversely, the mesenchymal markers fibronectin, N‐cadherin and vimentin, the EMT‐TFs Snail, Slug, Zeb1 and Zeb2, and the cancer stem cell markers CD44, Sox2 and Id1 were strongly induced by TGFβ and repressed by BMP in 3D cultures." (PMID 35348275, 2022). "ZEB2 is important in EMT-related processes such as cancer growth, drug resistance, cancer stem cells, apoptosis, survival, cell cycle arrest, cancer recurrence, and metastasis." (PMID 35992812, 2022).
cancer (continued). "To further examine the prognostic potential of ZEB2 in different cancer types, we analyzed the PrognoScan database." (PMID 35723302, 2022). "In the statement, experts emphasized central roles of transcription factors belonging to the ZEB families (Zeb1 and Zeb2) in the execution of EMT in cancer metastasis." (PMID 35915456, 2022). "We explored the correlation between ZEB2 and infiltrating immune cells in various cancers, including OV, using the TIMER database." (PMID 35723302, 2022). "This study explored the specific expression of ZEB2 in 33 human cancers and found there to be significant differences between several tumors." (PMID 36072677, 2022). "Currently, several histone modification regulators, including DOT1L, DNMT1, EZH2, and KDM5B, have been reported to play a role in the TGFβ-stimulated ZEB2 transcriptional upregulation of many cancers." (PMID 35606881, 2022). "It is well-known that the miR-200 family suppresses the EMT by inhibiting E-cadherin transcriptional repressors ZEB1 and ZEB2 in various types of cancers." (PMID 34208375, 2021). "In contrast, HLA-J and ZEB2 dependencies contained substantial dependent cell lines derived from other types of cancer such as pancreas, lung, and liver in addition to a substantial population of skin cells." (PMID 33842927, 2021). "TCGA database shows that LINC01296 level was significantly positively correlated with ZEB1 and ZEB2 levels in different cancers." (PMID 33854632, 2021). "Rescue experiments found miR-383-5p mimics reversed ZEB2 expression and the cancer-promoting effects of circCRIM1." (PMID 34847936, 2021). "Further, the E3-ubiquitin ligase FBXW7 directly binds and degrades ZEB2 in a phosphorylation-dependent manner, affecting ZEB2 levels in cancer tissues." (PMID 34356053, 2021). "Intriguingly, it has been shown that both Ovol2 and Zeb2 modulate cellular plasticity by fine-tuning the hybrid epithelial/mesenchymal states of Cd44+ cancer cells." (PMID 33989778, 2021). "It has been demonstrated that lncRNA-ATB promotes ZEB1 and ZEB2, thereby cause EMT, attack from cancer cells, and spread of cancer." (PMID 34200243, 2021). "Although miR-144 downregulated ZEB1 and ZEB2 in various types of cancers, this is the first study to investigate the interaction of ZEB1/2 and miR-144 in CRA." (PMID 34226299, 2021). "Previously, we published that ZEB2 induces resistance to DNA damage‐induced apoptosis in carcinoma cells." (PMID 33931939, 2021). "Through it, we identified a crucial knowledge gap wherein the relationship between miRs, ZEB2, and immune cells in the cancer context is still a mystery." (PMID 32664703, 2020). "PDGF signaling has been related to increased EMT markers such as TWIST, SNAIL, ZEB1 and ZEB2 through several pathways in cancer cell-MSC interactions." (PMID 32726910, 2020). "ZEB2 is a two-handed zinc finger transcription repressor which was found to be overexpressed in several cancer cell lines." (PMID 32046742, 2020). "In six of these eight cancers, an inverse pattern for ZEB2 mRNA expression was also observed (i.e., lower expression in tumors as compared with normal tissues)." (PMID 33066331, 2020). "Zeb1 and Zeb2 remarkably enhanced cancer stem cells in the head and neck in comparison with the ones in non-CSCs." (PMID 32280305, 2020). "Taken together, stimulation of ZEB2 by lncRNAs not only enhances metastasis of cancer cells via EMT induction, but also promotes cell proliferation." (PMID 32664703, 2020). "It is held that lncRNA HOTAIRM1 diminishes the expression of miR-873-5p to induce ZEB2, resulting in an increase in cancer cell proliferation and suppressing apoptotic cell death." (PMID 32664703, 2020). "In this section, we provide an overview of ZEB1 and ZEB2 proteins to shed some light on their role in cancer cells." (PMID 32664703, 2020). "E2F1 is implicated in regulating Zeb1 and Zeb2 expression, which promotes EMT, and MMP9, which drives cancer cell invasion." (PMID 32224870, 2020).